GABRG2 (gamma-aminobutyric acid type A receptor subunit gamma2)
Description:
Gamma subunit of the heteropentameric ligand-gated chloride channel gated by gamma-aminobutyric acid (GABA), a major inhibitory neurotransmitter in the brain. GABA-gated chloride channels, also named GABA(A) receptors (GABAAR), consist of five subunits arranged around a central pore and contain GABA active binding site(s) located at the alpha and beta subunit interface(s). When activated by GABA, GABAARs selectively allow the flow of chloride anions across the cell membrane down their electrochemical gradient. Gamma-2/GABRG2-containing GABAARs are found at both synaptic and extrasynaptic sites (By similarity). Chloride influx into the postsynaptic neuron following GABAAR opening decreases the neuron ability to generate a new action potential, thereby reducing nerve transmission (By similarity). GABAARs containing alpha-1 and beta-2 or -3 subunits exhibit synaptogenic activity; the gamma-2 subunit being necessary but not sufficient to induce rapid synaptic contacts formation. Extrasynaptic gamma-2-containing receptors contribute to the tonic GABAergic inhibition (By similarity). GABAARs function also as histamine receptor where histamine binds at the interface of two neighboring beta subunits and potentiates GABA response in a gamma-2 subunit-controlled manner (By similarity).
Synonyms: CAE2; DEE74; ECA2; EIEE74; FEB8; GEFSP3
Tractability: Small molecule: an approved drug acts on it; a structure with a bound ligand is known; a high-quality ligand is known; it belongs to a druggable protein family. Antibody: UniProt places it where antibodies can reach, with high confidence; its Gene Ontology location is reachable by antibodies, with high confidence; UniProt predicts a signal peptide or a membrane-spanning region. PROTAC: ubiquitination databases record sites on it; its protein half-life has been measured; a small molecule that binds it is known.
Safety:
Unwanted effects reported when the protein is acted on. In parentheses: how it was acted on, where the effect was seen, and who reports it.
ataxia (activation, acute dosing; central nervous system, cardiovascular; source: Lynch et al. (2017))
convulsions (inhibition, acute dosing; central nervous system, cardiovascular; source: Lynch et al. (2017))
decreased anxiety (activation, acute dosing; central nervous system, cardiovascular; source: Lynch et al. (2017))
decreased blood pressure (activation, acute dosing; central nervous system, cardiovascular; source: Lynch et al. (2017))
decreased body temperature (activation, acute dosing; central nervous system, cardiovascular; source: Lynch et al. (2017))
decreased cardiac contractility (activation, acute dosing; central nervous system, cardiovascular; source: Lynch et al. (2017))
decreased convulsions (activation, acute dosing; central nervous system, cardiovascular; source: Lynch et al. (2017))
decreased locomotor activity (activation, acute dosing; central nervous system, cardiovascular; source: Lynch et al. (2017))
decreased memory (activation, acute dosing; central nervous system, cardiovascular; source: Lynch et al. (2017))
decreased pain (activation, acute dosing; central nervous system, cardiovascular; source: Lynch et al. (2017))
decreased sleep (inhibition, acute dosing; central nervous system, cardiovascular; source: Lynch et al. (2017))
drug abuse/dependence (activation, acute dosing; central nervous system, cardiovascular; source: Lynch et al. (2017))
increased cardiac output (activation, acute dosing; central nervous system, cardiovascular; source: Lynch et al. (2017))
increased eating (activation, acute dosing; central nervous system, cardiovascular; source: Lynch et al. (2017))
increased respiratory rate (activation, acute dosing; central nervous system, cardiovascular; source: Lynch et al. (2017))
increased sleep (activation, acute dosing; central nervous system, cardiovascular; source: Lynch et al. (2017))
muscle relaxation (activation, acute dosing; central nervous system, cardiovascular; source: Lynch et al. (2017))
Gene: Protein-coding gene on chromosome 5 (162,000,057 to 162,162,977, forward strand). Ensembl gene ENSG00000113327.
Subcellular location: Postsynaptic cell membrane; Cell membrane; Cell projection, dendrite; Cytoplasmic vesicle membrane
Pathways (Reactome):
Neuronal System: GABA receptor activation
Signal Transduction: Signaling by ERBB4
Gene Ontology:
Molecular function: GABA-A receptor activity; GABA-gated chloride ion channel activity; protein binding; benzodiazepine receptor activity; chloride channel activity; extracellular ligand-gated monoatomic ion channel activity; monoatomic ion channel activity; transmembrane signaling receptor activity; transmitter-gated monoatomic ion channel activity involved in regulation of postsynaptic membrane potential
Biological process: chloride transmembrane transport; gamma-aminobutyric acid signaling pathway; inhibitory synapse assembly; cellular response to histamine; extrasynaptic signaling via GABA; negative regulation of synaptic transmission, GABAergic; synaptic transmission, GABAergic; chloride transport; monoatomic ion transmembrane transport; monoatomic ion transport; regulation of postsynaptic membrane potential
Cellular component: chloride channel complex; GABA-A receptor complex; plasma membrane; postsynaptic membrane; cytoplasmic vesicle membrane; dendrite membrane; postsynapse; postsynaptic specialization membrane; axon; dendrite; GABA-ergic synapse; membrane
Genetic constraint (gnomAD): Loss-of-function variants: 13 observed, 48.27 expected, observed/expected ratio (o/e) 0.27, 90% interval 0.17 to 0.43. The upper end of that interval is the gene's LOEUF score, 0.43, which puts it in group 1 of 6, group 1 being the genes least tolerant of losing a copy. Missense variants: 288 observed, 537.39 expected, observed/expected ratio (o/e) 0.54, 90% interval 0.49 to 0.59. Synonymous variants: 186 observed, 193.29 expected, observed/expected ratio (o/e) 0.96, 90% interval 0.85 to 1.09.
Gene-disease validity (ClinGen):
ClinGen rates the evidence that GABRG2 causes each of these diseases.
epilepsy (autosomal dominant): Definitive. A brain disorder characterized by episodes of abnormally increased neuronal discharge resulting in transient episodes of sensory or motor neurological dysfunction, or psychic dysfunction.
Homologues: Orthologues: chimpanzee GABRG2 (99% identical), guinea pig GABRG2 (99% identical), macaque GABRG2 (99% identical), dog GABRG2 (99% identical), pig GABRG2 (99% identical), mouse Gabrg2 (99% identical), rat Gabrg2 (99% identical), rabbit GABRG2 (97% identical), tropical clawed frog gabrg2 (89% identical), zebrafish gabrg2 (84% identical). Paralogues in human: GABRG1 (72% identical), GABRG3 (66% identical), GABRA4 (43% identical), GABRA6 (42% identical), GABRE (42% identical), GABRA1 (41% identical), GABRA3 (41% identical), GABRA5 (41% identical), GABRA2 (40% identical), GABRB2 (35% identical), GABRB1 (34% identical), GABRB3 (33% identical), and 33 more.
Diseases named in the same sentence as GABRG2 in open-access papers:
GABRG2 is named in the same sentence as 94 diseases in open-access papers, as found by Europe PMC text mining. Sharing a sentence is not in itself a finding about the gene and the disease. The quoted sentences say what the papers report.
epilepsy (60 papers, 2007 to 2026). "The first report of an epilepsy‐associated GABAA receptor variant was the GABRG2 p.(Lys328Met) variant." (PMID 37621067, 2024). "The PPI network of the DEGs at both 3 dpf and 5 dpf was established with the STRING database, showing the involvement of interleukin‐2 (IL‐2) receptor signal pathway in the differential phenotypes of epilepsy caused by GABRG2 mutations." (PMID 38357846, 2024). "We also compared different phenotypes and analyzed the brain transcriptomic changes of the epilepsy models induced by different GABRG2 mutations." (PMID 38357846, 2024). "The data presented here support the link between FS, epilepsy, and GABRG2 variants, shedding light on the relationship between the variant topological occurrence and disease severity." (PMID 36979350, 2023). "Further analysis showed that the GABRG2 missense variants associated with severe epilepsy phenotypes were mainly clustered in the transmembrane region from the M1 region to the M3 domain." (PMID 35359574, 2022). "Although the clinical phenotype of Dravet syndrome connected to GABRG2(Q390X) is amongst the most severe epilepsies, other disease-associated mutations in GABR subunits share some of the molecular pathomechanisms." (PMID 35327449, 2022). "GABRG2 (Gamma-Aminobutyric Acid Type A Receptor Subunit Gamma 2) has been associated with a plethora of neuro(developmental) disorders, mostly related to epilepsy." (PMID 35274098, 2022). "To date, GABRG2 variants have been reported in 58 patients who presented with epilepsy in multiple epilepsy centers." (PMID 35359574, 2022). "The genotype and phenotype of 58 patients reported in literature with GABRG2 variants related to epilepsy." (PMID 35359574, 2022). "Extensive work from previous studies has shown that GABRG2 mutations are associated with a wide spectrum of seizure disorders." (PMID 36077081, 2022). "Pathogenic GABRG2 variants have been reported in patients with epilepsy, developmental delays and behavioral disorders." (PMID 35359574, 2022). "The phenotypic spectrum of GABRG2 variants extends to the pharmacoresistant epilepsies, including Dravet syndrome and developmental epileptic encephalopathies (DEEs)." (PMID 35359574, 2022). "In 35 children with epilepsy carrying GABRG2 variants, the seizure onset age ranged from 2 days to 34 months of age (median age: 9 months)." (PMID 35359574, 2022). "This expands the clinical phenotype spectrum of GABRG2 mutations in epilepsy and further strengthens the notion of overlapping clinical phenotypes between GABRG2, GABRB3, and possibly other GABR mutations." (PMID 36077081, 2022). "With the broad application of next-generation sequencing (NGS) in patients with epilepsy, pathogenic variants of GABRG2 related to developmental and epileptic encephalopathy 74 (DEE74, OMIM:618396) were reported." (PMID 35359574, 2022). "We have extensively studied the molecular pathophysiology of the mutations in GABRG2 associated with either mild or severe epilepsy in vitro to in vivo." (PMID 34281185, 2021). "It is well known that mutations/variants in GABRA1, GABRB2, GABRB3, or GABRG2 produce several different types of epilepsy." (PMID 34095830, 2021). "GABRG2 mutations in epilepsy target different functional domains and influence GABAAR gating, membrane trafficking, and clustering at synapses." (PMID 34050134, 2021). "We demonstrated that the mutations in GABRG2 associated with severe epilepsy have mutant protein accumulation and aggregation, while the mutations in the same gene associated with mild epilepsy do not have the mutant protein accumulation and aggregation." (PMID 34281185, 2021). "In our studies, the GABRG2(Q390X) mutation associated with severe epilepsy diminished the expression of the wildtype partnering subunits and reduced the function of the remaining GABAA receptors." (PMID 34281185, 2021).
epilepsy (continued). "In particular, numerous mutations in the GABRG2 gene have been reported to cause epilepsy, about half of which interrupt normal protein translation (i.e. nonsense, splice-site or genomic deletion)." (PMID 31582559, 2019). "In particular, a heterozygous knock-in (KI) mouse model bearing the GABRG2 Q390X mutation has been generated, and displays reduced cortical inhibition associated with epilepsy phenotypes." (PMID 31582559, 2019). "Here we focused on three nonsense mutations in GABRG2 (GABRG2(R136*), GABRG2(Q390*) and GABRG2(W429*)) associated with epilepsies of different severities." (PMID 27762395, 2016). "We have demonstrated that nonsense GABRG2 mutations result in loss-of-function but different nonsense mutations are associated with epilepsy phenotypes with different severities." (PMID 27762395, 2016). "Missense or nonsense mutations of GABRA1, GABRB3 and GABRG2 epilepsy genes are linked with classical GEs with autosomal dominant inheritance including, GEFS+, childhood absence epilepsy, febrile seizures, and juvenile myoclonic epilepsy." (PMID 27622563, 2016). "Mutations in several GABAAR subunit‐encoding genes, including the synaptic subunits GABRA1, GABRB3, and GABRG2 that associate with gephyrin, have been identified in epilepsy syndromes of different degrees of severity." (PMID 26613940, 2015). "Regarding the GABRG2 C588T gene polymorphism, the C allele and C- included genotypes were more frequent among healthy children, whereas the T allele and T-included genotypes were more frequent among patients with epilepsy." (PMID 41146305, 2025). "Although some studies have investigated the relationship between genotypes and phenotypes of epilepsy induced by different GABRG2 mutations, the mechanisms remain unclear." (PMID 38357846, 2024). "To further investigate the complicated relationship between phenotypes and genotypes, we have established zebrafish epilepsy models overexpressing different mutant human GABRG2, including the F343L mutation located in the TM36 and the I107T mutation located in the N‐terminal." (PMID 38357846, 2024). "Our data indicated that differential inflammation responses might determine the variable phenotypes of epilepsy induced by GABRG2 mutations." (PMID 38357846, 2024). "Our findings here support the prior study on HRD1, proteostasis regulators, and genetic epilepsies and suggest that this class of drug could be repurposed for at least a subset of epilepsies caused by mutations like GABRG2(Q390X)." (PMID 38731820, 2024). "All these data together suggested the GABRG2 R43Q pathogenic variant may be responsible for the absence epilepsy." (PMID 40217359, 2023). "Epilepsy, growth retardation, and behavioral disorders may be related to pathogenic GABRG2 variants." (PMID 37275237, 2023). "However, the prognosis of patients with GABRG2-related epilepsy is better than that of patients carrying variants in the other three genes." (PMID 35359574, 2022). "Therefore, this study aimed to determine the phenotypic spectrum of epilepsy patients carrying GABRG2 variants and the prognosis of patients in a Chinese cohort from multicenter." (PMID 35359574, 2022). "Several mutations in GABRG2 cause epilepsy, including GABRG2(Q390X) found in Dravet syndrome." (PMID 35327449, 2022). "Here, we identified 31 novel and 4 previously reported GABRG2 variants in patients with epilepsy." (PMID 35359574, 2022). "Of the 58 patients with GABRG2 variants reported previously, the epilepsy phenotypes were varied." (PMID 35359574, 2022). "In 2013, Carvill reported a male patient with epilepsy presenting myoclonic-atonic seizures (EMAS) who carried a GABRG2 variant (p.R323Q) and experienced multiple seizure types, including GTCS, absence seizures, atonic seizures, myoclonic seizures, and tonic-clonic seizures." (PMID 35359574, 2022). "Gabrg2 loss-of-function mouse models exhibit different epilepsy phenotypes." (PMID 34050134, 2021).
epilepsy (continued). "Three diagnoses resulted from an internal analysis of new disease–gene associations, in which GABRG2 linked to sleep-related hypermotor epilepsy (SHE, we have performed in vitro experiments to investigate these GABRG2 variants’ function but the results have not yet been published)." (PMID 33391346, 2020). "Thus, in this study we aimed to establish and characterize a new in vivo genetic model of epilepsy caused by mutations in the GABRG2 gene." (PMID 31582559, 2019). "It is well known that missense mutations in coding sequences in the GABAA receptor γ2 subunit gene GABRG2 are associated with relatively mild epilepsy phenotypes, including childhood absence epilepsy and febrile seizures, and with the genetic epilepsy with the febrile seizures plus (GEFS+) spectrum." (PMID 28197552, 2017). "Mutations in GABRG2 are associated with epilepsies of varying severities." (PMID 27762395, 2016). "Mutations in GABAA receptor subunit genes are frequently associated with epilepsy, and nonsense mutations in GABRG2 are associated with several epilepsy syndromes including childhood absence epilepsy, generalized tonic clonic seizures and the epileptic encephalopathy, Dravet syndrome." (PMID 27762395, 2016). "However, whether neuroinflammation is involved in other phenotypes of epilepsy induced by GABRG2 mutations and is related to the severity of epilepsy needs further exploration." (PMID 38357846, 2024). "Genetic/molecular endophenotypes (11.3%, n = 6) explored modifier genes (e.g., GABRG2, SCN1A), polygenic risk scores, and epigenetic markers relevant to epilepsy risk and treatment response." (PMID 41440071, 2025). "γ2 subunit (encoded by GABRG2) plays an important role in GABAA receptor functions and mutations of γ2 subunit often induce the occurrence of epilepsy." (PMID 38357846, 2024). "Increased pro‐inflammatory cytokines including tumor necrosis factor‐alpha (TNF‐α), IL‐1β, and IL‐6 were also observed in an epilepsy mouse model with Gabrg2+/Q390X knockin, indicating neuroinflammation was one of the mechanisms for genetic epilepsy." (PMID 38357846, 2024). "In the previous research, we established zebrafish epilepsy models by expressing mutant human GABRG2(F343L) and GABRG2(I107T), which were discovered in patients." (PMID 38357846, 2024). "FS are relatively common in GABAA receptor‐associated epilepsies caused by variants in GABRA1, GABRB3 or GABRG2." (PMID 37621067, 2024). "During the very beginning of genetic epilepsy, with the studies of large families, SCN1A, SCN1B, and GABRG2 were identified as genes for monogenic epilepsies." (PMID 40217359, 2023). "Variants in GABRG2 have been associated with a wide range of epileptic syndromes, from mild cases of FS and CAE to more severe forms of epilepsy such as Dravet syndrome." (PMID 36979350, 2023). "Variations of GABRG2 (NM_198904, GRCh37/hg19) were determined by targeted next-generation sequencing of epilepsy (epilepsy gene panel) or whole exome sequencing." (PMID 36979350, 2023). "Through a multicenter collaboration in China, we analyzed the genotype-phenotype correlation and antiseizure medication (ASM) of patients with GABRG2-related epilepsy." (PMID 35359574, 2022). "Genes potentially associated with FS-related epilepsy include SCN1A, ADGRV1, SCN1B, SCN9A, GABRG2, GABRD, and CPA6." (PMID 35813073, 2022). "The clinical features of GABRG2-related epilepsy included seizure onset, usually in infancy, and seizures were fever-sensitive." (PMID 35359574, 2022). "This study aimed to obtain a comprehensive understanding of the genetic and phenotypic aspects of GABRG2-related epilepsy and its prognosis and to explore the potential prospects for personalized medicine." (PMID 35359574, 2022).